ANGPTL4 (angiopoietin like 4)
Diseases named in the same sentence as ANGPTL4 in open-access papers (continued):
Sharing a sentence is not in itself a finding about the gene and the disease.
myocardial infarction (8 papers, 2014 to 2025). Gross necrosis of the myocardium, as a result of interruption of the blood supply to the area, as in coronary thrombosis. "It has been observed in mice with acute myocardial infarction that the elevated ANGPTL4 level is caused by hypoxia, which has a protective effect on the heart and can even be used to predict the prognosis of the disease." (PMID 38425231, 2024). "The ability of ALG@dECM to promote angiogenesis, regulate macrophage behavior, and potentially activate ANGPTL4‐mediated metabolic regulation further validates the importance of hydrogel‐based ECM in treating myocardial infarction." (PMID 40200862, 2025). "Previous studies on peritonitis and myocardial infarction have demonstrated that ANGPTL4 primarily exhibits anti-inflammatory effects by reducing inflammatory cell infiltration and pro-inflammatory cytokine release." (PMID 39910592, 2025). "In vitro studies have shown that ANGPTL4 can alleviate apoptosis and oxidative stress of bone marrow mesenchymal stem cells induced by hypoxia and alleviate myocardial damage in rats with myocardial infarction." (PMID 38425231, 2024). "We showed that acute myocardial infarction (AMI) patients with higher levels of ANGPTL4 had fewer vascular events than AMI patients with lower levels of ANGPTL4 (p < 0.05)." (PMID 36782020, 2023). "The significance of the MSC secretome, such as angiopoietin-like 4, is a promising candidate for novel concepts of systolic heart failure from myocardial infarction." (PMID 36015285, 2022). "ANGPTL4 treatment increased the antiinflammatory macrophages in the myocardial infarction animal model and markedly improved cardiac function." (PMID 34422410, 2021). "Furthermore, administration of recombinant ANGPTL4 was effective as a treatment for acute myocardial infarction because it counteracts the increase in permeability observed in re-perfused acute myocardial infarction." (PMID 24721177, 2014). "Angptl4 has been shown to reduce the size of myocardial infarction and no-reflow in rats, and this effect is attributed to the preservation of vascular integrity by protecting VE-cadherin complex." (PMID 29912977, 2018).
non-small cell lung carcinoma (8 papers, 2021 to 2025). A group of at least three distinct histological types of lung cancer, including non-small cell squamous cell carcinoma, adenocarcinoma, and large cell carcinoma. "Importantly, high levels of ANGPTL4 can significantly enhance the resistance of non-small cell lung cancer (NSCLC) cells to radiation." (PMID 40328736, 2025). "ANGPTL4 may be an important regulator of EGFR-TKI resistance in patients with non-small-cell lung cancer." (PMID 36467503, 2022). "In non-small cell lung cancer (NSCLC), ANGPTL4 is significantly overexpressed compared to normal tissue." (PMID 40723247, 2025). "Angiopoietin-like protein 4 (ANGPTL4) is a glycoprotein secreted by various cells; it belongs to the Angiopoietin family (ANGPTL) and is overexpressed in non-small cell lung cancer." (PMID 34323652, 2021). "Targeting ANGPTL4 may inhibit the development of EGFR-TKI resistance, which may improve the survival rate of patients with non-small-cell lung cancer." (PMID 36467503, 2022).
pneumonia (8 papers, 2019 to 2026). An acute, acute and chronic, or chronic inflammation focally or diffusely affecting the lung parenchyma, caused by an infection in one or both of the lungs (by bacteria, viruses, fungi, or mycoplasma.). "In murine influenza and pneumonia models, elevated ANGPTL4 is associated with increased vascular permeability." (PMID 40006981, 2025). "ANGPTL4 expression was reported to be elevated and involved in lung damage during infection caused by numerous stimuli, such as influenza pneumonia." (PMID 36352407, 2022). "We previously showed that upregulation of the C-terminal ANGPTL4 fragment (cANGPTL4) was associated with increased severity of pulmonary leakage and damage in primary influenza pneumonia." (PMID 31164474, 2019). "It was reported that angiopoietin-like 4 (ANGPTL4) could be a diagnostic biomarker and a therapeutic target for pneumonia." (PMID 37821811, 2023). "In LPS or influenza pneumonia induced lung injury, ANGPTL4 is upregulated in lung alveolar epithelial cells, where it promotes immune infiltration and inflammation." (PMID 40723247, 2025). "The further development of antibodies targeting ANGPTL4 is a promising area of research for the treatment of several diseases, including cancer, pneumonia, and retinopathies." (PMID 40723247, 2025). "In respiratory infection, ANGPTL4 contributes to pathology during influenza pneumonia as well as in secondary pneumococcal pneumonia." (PMID 39022746, 2024). "ANGPTL4 knockout (−/−) mice exhibit reduced pulmonary edema and improved lung tissue integrity in primary influenza pneumonia." (PMID 31164474, 2019). "It was found that ANGPTL4 expression level was upregulated in pneumonia, and it was involved in angiogenesis and regulation of vascular permeability, inflammatory response, lung tissue leakiness and injury, lipid and carbohydrate metabolism, wound healing, tumorigenesis, etc.." (PMID 37821811, 2023). "Notably, it was reported that the expression level of cANGPTL4, one of isoforms of ANGPTL4 proteolysis, was mainly upregulated in patients with pneumonia." (PMID 37821811, 2023). "In our study, we have shown that ANGPTL4 expression is readily induced and expressed upon H. pylori infection in the gastric tissues as well as GECs, which is consistent with the other reports about the increased expressions of ANGPTL4 in the lung tissues with influenza pneumonia." (PMID 39022746, 2024). "A study on community-acquired pneumonia revealed that ANGPTL4 levels were about 3.2 times higher in patients with severe pneumonia than those with non-severe disease (median of 1441.70 pg/mL versus 453.53 pg/mL, p < 0.001)." (PMID 40006981, 2025).
rheumatoid arthritis (8 papers, 2014 to 2023). A chronic, systemic autoimmune disorder characterized by inflammation in the synovial membranes and articular surfaces. "Higher Angptl4 concentrations have been reported in patients on hemodialysis and in patients suffering from rheumatoid arthritis." (PMID 34951653, 2022). "Rheumatoid arthritis patients with high serum concentrations of ANGPTL4 also have high serum levels of RANKL, a circulating marker of bone erosion." (PMID 29739381, 2018). "Recently, the reported studies showed that ANGPTL4 might be functional in some musculoskeletal pathologies, such as rheumatoid arthritis (RA), osteoarthritis, and osteoporosis." (PMID 34876931, 2021). "An unusually large fraction of samples from patients with rheumatoid arthritis (RA) (37% of all sera analyzed) were reported to have levels of ANGPTL4 higher than 170 ng/ml." (PMID 28107351, 2017). "Our aim was to study whether the previously reported high levels of ANGPTL4 detected in serum from patients with rheumatoid arthritis (RA) by ELISA was due to any specific molecular form of this protein (oligomers, monomers or fragments)." (PMID 28107351, 2017).
COVID-19 (7 papers, 2022 to 2025). A disease caused by infection with severe acute respiratory syndrome coronavirus 2. "Recently it was shown that propranolol can be used to suppress the formation of hemangiomas in the lungs of COVID-19 patients by suppressing the expression of ANGPTL4, providing a potential mechanism of action for propranolol in treating hemangiomas." (PMID 40723247, 2025). "In acute respiratory distress syndrome, COVID-19, and Kawasaki disease, elevated ANGPTL4 levels correlate with disease severity and poor clinical outcomes." (PMID 40006981, 2025). "Migration of ZHX3, an ANGPTL4 repressor, from the slit diaphragm into the podocyte nucleus by COVID-19 cocktails parallels similar observations in human and experimental FSGS." (PMID 37040185, 2023). "Thus, ANGPTL—mainly ANGPTL4 through the NRP-1 receptor—could be the potential link between COVID-19 and AIS." (PMID 36009579, 2022). "Angiopoietin-like 4 (ANGPTL4) is induced by hypoxia as well as hypoxia-inducible factor 1 (HIF-1), and is a novel marker of COVID-19 severity." (PMID 38634132, 2024).
esophageal squamous cell carcinoma (7 papers, 2013 to 2024). Esophageal squamous cell carcinoma (ESCC) is a type of esophageal carcinoma (EC) that can affect any part of the esophagus, but is usually located in the upper or middle third. "Two clinical studies have investigated ANGPTL4's specific prognostic role in esophageal cancer, including esophageal squamous cell carcinoma." (PMID 37688629, 2023). "The aim of this study was to examine ANGPTL4 expression in tumor and serum tissues from esophageal squamous cell carcinoma (ESCC) patients." (PMID 23925665, 2013). "Indeed, it has been demonstrated that ANGPTL4 contributes to metastasis by stimulating cell invasion in head and neck carcinoma, in esophageal squamous cell carcinoma (ESCC) and oral squamous cell carcinoma (OSCC) patients." (PMID 29389861, 2018).
glomerular disease (7 papers, 2014 to 2026). "Further, ANGPTL-4 expressed in podocytes was found to be related to increased albuminuria, suggesting a role of ANGPTL-4 in overt proteinuria in glomerular diseases." (PMID 37108963, 2023). "While Zhx1 inhibited the apoptosis of glioblastoma cells by regulating the expression of Bcl2 and Bax and induced early proteinuria and primary glomerular disease by upregulating the Angptl4 expression." (PMID 37452012, 2023). "Urinary Angptl4 levels were elevated in MCD in relapse as well as in patients with massive proteinuria due to other glomerular diseases." (PMID 28441404, 2017). "The discovery of a central, mechanistic role played by two different forms of the secreted glycoprotein angiopoietin-like 4 (Angptl4) in human and experimental glomerular disease has opened new treatment avenues." (PMID 24611049, 2014). "We found that ANGPTL4 is significantly expressed in podocytes under various glomerular diseases and healthy conditions and then mapped the distribution of ANGPTL4 across podocyte subcompartments, confirming its superiority as a universal marker over traditional SRM markers." (PMID 39776814, 2025). "Urinary Angptl4 excretion was increased in patients with massive proteinuria regardless of underlying glomerular disease (MCD, FSGS and MN) compared to control subjects (p<0.0001 for each group." (PMID 28441404, 2017). "Angptl4 podocyte overexpression has been reported in MCD in relapse and in other human glomerular diseases." (PMID 28441404, 2017). "Elevated urinary Angptl4 n glomerular disease appears to reflect the degree of proteinuria rather than any specific disease." (PMID 28441404, 2017). "Molecular pathways leading up to sustained Angptl4 upregulation in MCD, and not in other primary glomerular diseases, have not as yet been published." (PMID 24611049, 2014).
kidney cancer (7 papers, 2010 to 2026). Primary or metastatic malignant neoplasm involving the kidney. "In particular, among 151 dual-role genes detected by Moonlight one interesting gene, ANGPTL4, was predicted to be an oncogene in kidney cancers with associated promoter peaks as well as a tumor suppressor in prostate adenocarcinoma with hypermethylation in the promoter region." (PMID 31900418, 2020). "Recent discoveries revealed that ANGPTL4 was involved in angiogenesis, altered redox regulation, and metastasis, so we decided to investigate its role in kidney cancer progression." (PMID 24260413, 2013). "Moreover, serum ANGPTL4 levels are even higher in RCC patients than in patients with other solid tumors, indicating that ANGPTL4 may play a more specific role in the development and progression of kidney cancer." (PMID 39840089, 2024).
liver cancer (7 papers, 2013 to 2026). An epithelial or non-epithelial malignant neoplasm that arises from the liver. "All the results above provide new insights into better understanding biological indicators, such as XPO4, TGFβ1, ANGPTL4 and elF5A2, in the prediction and evaluation of liver cancer, as well as signaling pathways in the control of liver cancer." (PMID 23251252, 2013). "Furthermore, pan-cancer analysis revealed ANGPTL4 overexpression in PC, as well as breast, colorectal, and liver cancers." (PMID 41522514, 2026). "Previously it was reported that treatment of mouse primary hepatocytes with peroxisomes proliferators (including Wy14643) for 24 hours led to upregulation of 11 genes related to liver cancer (i.e. Angptl4, Bnip3, Dbi, Fabp1, Fabp2, Fasn, HifIa, Lgals3, Ly6d, Mgll, SerpineI)." (PMID 25511156, 2014). "Therefore, we employed multiple methods to assess TGFβ, XPO4, elF5A2 and ANGPTL4 in cancerous and paracancerous liver tissue samples obtained from 280 patients suffering from liver cancer." (PMID 23251252, 2013). "In the present study, we employed multiple techniques, including the use of qPCR, immunostaining and TMAs, as well as histology and pathology analysis, to undertake a study to evaluate XPO4, TGFβ1, ANGPTL4 and elF5A2 in carcinoma and paracarcinoma tissues from 280 liver cancer patients." (PMID 23251252, 2013). "Importantly, clinical datasets further supported the correlations between GFPT1/ANGPTL4 expression and cholesterol levels in Non-Alcoholic Steatohepatitis (NASH) liver cancer patients." (PMID 40806239, 2025).
liver fibrosis (7 papers, 2021 to 2025). "ANGPTL4 deficiency reportedly increases free cholesterol levels and promotes liver fibrosis in patients with NASH." (PMID 39338294, 2024). "In terms of mechanism, in a study based on a non-alcoholic steatohepatitis mouse model, ANGPTL4 deficiency could lead to the accumulation of free cholesterol, thereby promoting the progression of liver fibrosis." (PMID 41169876, 2025). "Recent studies have reported a close association between ANGPTL4 and pulmonary and hepatic fibrosis, potentially through mediating fibrogenesis through mechanisms such as inflammatory responses, excessive tissue repair, vascular genesis, and epithelial–mesenchymal transition." (PMID 38992710, 2024). "Pro-fibrotic effects of Angptl4 have been reported in lung and kidney fibrosis, while in liver fibrosis Angptl4 acted in a protective manner." (PMID 39311911, 2024). "VEGF-R1, ANGPTL-4, Nidogen-1 have not been reported to be associated with the occurrence of liver fibrosis." (PMID 35659360, 2022). "The post-interventional dynamics of physiologically relevant adipokines and hepatokines (ANGPTL4, CCL5, GDF15, GPNMB, IGFBP6), as well as their correlation with fat mass reduction and improvement of liver fibrosis, were analyzed." (PMID 36430499, 2022). "This strongly predictive character for hepatic fibrosis was exclusively observed for GDF15 but not for ANGPTL4, CCL5, GPNMB, and IGFBP6." (PMID 36430499, 2022). "We determined ANGPTL-3 and ANGPTL-4 levels in five groups of clinical samples ranging from the acutely infected with almost no liver fibrosis to cirrhotic patients with HCC." (PMID 34360721, 2021). "Furthermore, in a nonalcoholic fatty liver disease model, the absence of ANGPTL4 leads to the accumulation of free cholesterol in hepatic stellate cells, thereby exacerbating liver fibrosis." (PMID 38992710, 2024).
membranous nephropathy (7 papers, 2014 to 2026). "Patients with biopsy-proven primary MCD, focal segmental glomerulosclerosis, membranous nephropathy (60, 52 and 52 respectively) and 18 control subjects had urinary and serum Angptl4 measured by Elisa." (PMID 28441404, 2017).
triple-negative breast carcinoma (7 papers, 2020 to 2025). An invasive breast carcinoma which is negative for expression of estrogen receptor (ER), progesterone receptor (PR), and human epidermal growth factor receptor 2 (HER2). "Recent works have shown that over-expression of ANGPTL4 is linked to the down-regulation of the mRNA levels of ECM-related genes in triple-negative breast cancer cell lines." (PMID 39811640, 2025). "The BCBM is promoted by the interaction of astrocytes in the brain and the invading triple-negative breast cancer cells via TGF-β2 (Transforming Growth Factor-beta-2) produced by astrocytes and is responsible for ANGPTL4 expression upregulation/angiopoietin-like 4 (ANGPTL4)." (PMID 34944840, 2021).
uveal melanoma (7 papers, 2016 to 2023). A melanoma derived from melanocytes of the uveal tract. "ANGPTL4 expression is induced by hypoxia which has been documented in lipedema adipose tissue due to dysregulated microvasculature, inflammation, and increases in interstitial fluid, and in cancer such as in uveal melanoma." (PMID 37686378, 2023). "A recent study carried out on patients with uveal melanoma (UM) showed that ANGPTL4 secretion is regulated by HIF-1 and cooperates with VEGF in the angiogenesis promotion, supporting the potential benefit of a combined VEGF-ANGPTL4 inhibition to increase the efficacy of antiangiogenic treatments." (PMID 28182091, 2017).
Arthritis (6 papers, 2012 to 2026). Inflammation of a joint. "ANGPTL-4 has likewise been linked with arthritis because it was identified in a gene expression profiling analysis as one of the most highly expressed genes in early CIA, a widely used mouse model of RA." (PMID 22866899, 2012). "ANGPTL-related signaling patterns differed among arthritis subtypes, with ANGPTL4 more prominent in OA and PsA and ANGPTL2 more frequently in RA-related transcriptional programs." (PMID 41751295, 2026). "ANGPTL4 implicated in the chondrogenic differentiation of MSCs, whereas HAS1 has been associated with osteophyte formation and arthritis." (PMID 38200556, 2024). "Angiopoietin-like 4 overexpression was first described in stromal fibroblasts within the joints of mice with collagen-induced arthritis." (PMID 28458654, 2017). "Increased ANGPTL4 expression during early stages of murine collagen-induced arthritis occurred specifically in stromal fibroblasts adjacent to blood vessels, suggestive of a role in angiogenesis." (PMID 28458654, 2017). "ANGPTL4 mRNA and protein levels have previously been reported to increase in the early stages of murine collagen-induced arthritis, where expression was specific to the stromal fibroblast-like cells adjacent to blood vessels, suggestive of a role in angiogenesis as reported in cancer." (PMID 25289668, 2014).